MRPL3 (mitochondrial ribosomal protein L3)
Synonyms: MRL3; RPML3; uL3m; COXPD9
Tractability: Small molecule: a structure with a bound ligand is known. PROTAC: ubiquitination databases record sites on it; its protein half-life has been measured.
Gene: Protein-coding gene on chromosome 3 (131,462,202 to 131,502,983, reverse strand). Ensembl gene ENSG00000114686.
Subcellular location: Mitochondrion
Pathways (Reactome):
Metabolism of proteins: Mitochondrial ribosome-associated quality control; Mitochondrial translation elongation; Mitochondrial translation initiation; Mitochondrial translation termination
Gene Ontology:
Molecular function: RNA binding; structural constituent of ribosome
Biological process: mitochondrial translation; translation
Cellular component: mitochondrial large ribosomal subunit; mitochondrion; mitochondrial inner membrane; ribosome
Genetic constraint (gnomAD): Loss-of-function variants: 19 observed, 19.86 expected, observed/expected ratio (o/e) 0.96, 90% interval 0.67 to 1.4. The upper end of that interval is the gene's LOEUF score, 1.4, which puts it in group 5 of 6, group 1 being the genes least tolerant of losing a copy. Missense variants: 223 observed, 249.26 expected, observed/expected ratio (o/e) 0.89, 90% interval 0.8 to 1. Synonymous variants: 114 observed, 97.28 expected, observed/expected ratio (o/e) 1.17, 90% interval 1.01 to 1.37.
Gene-disease validity (ClinGen):
ClinGen rates the evidence that MRPL3 causes each of these diseases.
mitochondrial disease (autosomal recessive): Moderate.
Homologues: Orthologues: chimpanzee MRPL3 (99% identical), macaque MRPL3 (96% identical), guinea pig MRPL3 (87% identical), rabbit MRPL3 (87% identical), pig MRPL3 (86% identical), dog MRPL3 (85% identical), rat Mrpl3 (83% identical), mouse Mrpl3 (82% identical), tropical clawed frog mrpl3 (66% identical), zebrafish mrpl3 (59% identical), Drosophila melanogaster mRpL3 (37% identical), Caenorhabditis elegans mrps-18C (31% identical).
Diseases named in the same sentence as MRPL3 in open-access papers:
MRPL3 is named in the same sentence as 25 diseases in open-access papers, as found by Europe PMC text mining. Sharing a sentence is not in itself a finding about the gene and the disease. The quoted sentences say what the papers report.
breast carcinoma (5 papers, 2019 to 2025). "MRPL3 is a component of the 39S subunit of the mitochondrial ribosome and is part of diagnostic and/or prognostic signatures for breast cancer, pancreatic carcinoma, and lung adenocarcinoma." (PMID 35954429, 2022). "The expression of the MRPL3 is upregulated in breast tumor tissues, positively correlating with cancer progression, receiver operating characteristic(ROC) curve and Kaplan-Meier survival analyses, which indicates its potential as a diagnostic and prognostic biomarker for breast cancer." (PMID 40371222, 2025). "In addition, models incorporating MRPL3 have demonstrated strong prognostic performance in lung and breast cancers 9,18." (PMID 40740231, 2025). "To further elucidate the lurking biological functions of CENPL, ISG20L2, MRPL3 and LSM4 in breast cancer occurrence and development, we conducted GSEA and GSVA using METABRIC dataset." (PMID 34341433, 2021). "DiseaseMeth version 2.0 analysis displayed that the mean methylation levels of CENPL, MRPL3 and LSM4 were all significantly reduced in breast cancer compared to normal breast tissues (P < 0.05)." (PMID 34341433, 2021). "The expression levels of each hub gene (CENPL, ISG20L2, MRPL3, and LSM4) was correlated with EZH2 in three different breast cancer cell lines (p < 0.01)." (PMID 34341433, 2021). "Based on the TCGA_BRCA and match TCGA normal and GTEx data of GEPIA database, the mRNA expression levels of these genes (CENPL, ISG20L2, MRPL3 and LSM4) were also significantly higher in breast cancer tissues than normal tissues." (PMID 34341433, 2021). "Additionally, genetic alterations of CENPL, ISG20L2, MRPL3, and LSM4 were further examined in cBioPortal database, showing these four hub genes were altered in 570 (26%) of 2173 breast cancer patients." (PMID 34341433, 2021). "Generally speaking, the DNA methylation patterns negatively correlates with mRNA expression, which is consistent with the observed up-regulation of CENPL, MRPL3 and LSM4 in breast cancer, while the latest research suggested DNA hypermethylation can lead to mRNA upregulation." (PMID 34341433, 2021). "In DiseaseMeth 2.0 database, the correlation analysis of DNA methylation patterns of hub genes with mRNA expression revealed that CENPL, MRPL3 and LSM4 were hypomethylated in breast cancer samples compared with adjacent normal ones, while ISG20L2 was hypermethylated in breast cancer sample." (PMID 34341433, 2021). "Considering the five hub genes, which were identified based on PPI networks and WGCNA, share the same signaling pathways during breast cancer progression, we conducted correlation analysis between the four novel hub genes (CENPL, ISG20L2, LSM4 and MRPL3) and EZH2." (PMID 34341433, 2021). "For instance, breast cancer patients with high expression of MRPL3, a mitochondrial ribosomal protein that is not related to cancer in the literature, have reduced survival (log-rank p value ≈ 1.75 × 10−2)." (PMID 30778056, 2019). "Among these, many studies on EZH2 in breast cancer have been reported, but no studies are related to the roles of CENPL, ISG20L2, MRPL3 and LSM4 in breast cancer." (PMID 34341433, 2021). "As an oncogene, growing evidence has identified EZH2 was closely related to breast cancer development and progression through multiple molecular mechanisms, but no studies are related to the roles of CENPL, ISG20L2, MRPL3 and LSM4 in breast cancer." (PMID 34341433, 2021).
pancreatic carcinoma (4 papers, 2019 to 2025). "In conclusion, on the basis of TCGA sequence data, we proposed a four genes model (DNAH10, HSBP1L1, KIAA0513, and MRPL3), which facilitated the discernment of high‐risk patients for worse OS in pancreatic carcinoma." (PMID 31102348, 2019). "Immunohistochemical results showed that among the 8 CRGs: CEP55, FAM111B, MRPL3, MET, and KNSTRN had higher protein expression in pancreatic cancer tissues, while on the contrary, the protein expression of DHX30 in normal pancreas was significantly higher than that in pancreatic cancer tissues." (PMID 40677006, 2025).
hepatocellular carcinoma (3 papers, 2024 to 2025). A malignant tumor that arises from hepatocytes. "Elevated MRPL3 expression has been linked to poor prognosis in prostate cancer and hepatocellular carcinoma, correlating with advanced tumor stage and invasiveness 12,17." (PMID 40740231, 2025). "Experimental validation confirmed that silencing MRPL3 disrupted mitochondrial function and inhibited hepatocellular carcinoma cell proliferation, migration, and invasion." (PMID 41160759, 2025).
colorectal cancer (2 papers, 2019 to 2024). A primary or metastatic malignant neoplasm that affects the colon or rectum. "Previous report indicated MRPL3 was the candidate susceptibility genes for common familial colorectal cancer and RNA metabolism‐related genes in non‐small cell lung cancer." (PMID 31102348, 2019).
hypertrophic cardiomyopathy (2 papers, 2020 to 2025). A condition in which the myocardium is hypertrophied without an obvious cause. "MRPL3 mitochondrial ribosomal protein L3 was found to play a role in hypertrophic cardiomyopathy and help with protein synthesis in the mitochondria." (PMID 41160759, 2025). "Pathogenic mutations in MRPL3 were responsible for the clinical phenotype of combined oxidative phosphorylation deficiency-9 (COXPD9), in which severe hypertrophic cardiomyopathy is a central presentation." (PMID 33238645, 2020).
cervical cancer (1 paper, 2025). A primary or metastatic malignant neoplasm involving the cervix. "The genomic data from cBioPortal indicated that MRPL3 alterations were the most frequent in cervical cancer (25%)." (PMID 40740231, 2025).
liver cancer (1 paper, 2025). An epithelial or non-epithelial malignant neoplasm that arises from the liver. "Previous bioinformatics studies have indicated that MRPL3 is highly expressed and potentially prognostic in several cancers, including breast and liver cancers; however, these findings lack experimental validation, and the role of MRPL3 in PC remains unknown 9,12." (PMID 40740231, 2025).
lymph node metastasis (1 paper, 2021). "In this study, our data not only showed the expression level of CENPL, ISG20L2, LSM4 and MRPL3 were strongly associated with age, lymph node metastasis and higher SBR grade, but also significantly upregulated in triple negative breast cancer patients compared to non-triple negative breast cancer." (PMID 34341433, 2021).
Obesity (1 paper, 2023). Accumulation of substantial excess body fat. "Meanwhile, Mief1 (mitochondrial elongation factor 1), which lies in the dominant Fob2 (Fat line obesity QTL 2) confidence interval identified in our previous study, and Mrpl3 (mitochondrial ribosomal protein L3) encode proteins involved in mitochondrial translation and biogenesis." (PMID 36414820, 2023).
osteosarcoma (1 paper, 2020). A usually aggressive malignant bone-forming mesenchymal neoplasm, predominantly affecting adolescents and young adults. "Lately, MRPS7 was detected as a key gene in the pathophysiological process of osteosarcoma and the MRPL3 content is positively correlated with the prognosis of osteosarcoma." (PMID 33238645, 2020).
Pan (1 paper, 2025). "Pan-cancer univariate Cox regression analysis revealed that MRPL3 was a significant prognostic factor for disease-free survival (DFS) and OS, specifically in PC and uterine corpus endometrial carcinoma." (PMID 40740231, 2025).
pancreatic adenocarcinoma (1 paper, 2025). "The inclusion of MRPL3 in the prognostic model underscores the potential importance of MRPs in pancreatic adenocarcinomas." (PMID 39859078, 2025). "Interestingly, the GEPIA database has also revealed that 63 MRPs, including MRPL3, are significantly upregulated in pancreatic adenocarcinomas." (PMID 39859078, 2025).
cancer (8 papers, 2013 to 2025). A tumor composed of atypical neoplastic, often pleomorphic cells that invade other tissues. "Pan-cancer analysis of TCGA and GTEx datasets revealed significantly elevated MRPL3 expression across different cancer types, including BLCA, BRCA, CESC, CHOL, COAD, DLBC, and PAAD, compared to that in normal tissues." (PMID 40740231, 2025). "We analyzed the expression level of MRPL3 across 33 types of cancer and discovered that it was significantly elevated in tumor tissues for most cancers, including HCC." (PMID 39868366, 2024). "In all of these studies, MRPL3 levels were higher in cancer tissues compared to normal ones." (PMID 35954429, 2022). "Furthermore, MRPL3’s overexpression in HCC tissues and cell lines correlates with metabolic shifts toward glycolysis and lactate accumulation, hallmarks of cancer metabolism." (PMID 39868366, 2024).
tumor (7 papers, 2013 to 2026). "MRPL3 was nominated in tumor BCT40 as a C to G variant on chromosome 3 at coordinates 131220447 (chromosome 3: 131220447) with 53 reads supporting the reference allele (C) and 79 reads supporting the alternate allele (G)." (PMID 24223926, 2013). "In addition, patients with PC with high MRPL3 expression exhibited significantly higher tumor stemness scores, supporting the association between MRPL3 overexpression and aggressive tumor phenotypes." (PMID 40740231, 2025). "Western blot analysis of paired tumor and adjacent normal pancreatic tissues from 12 patients confirmed significantly elevated MRPL3 protein levels in PC tissues (p < 0.001)." (PMID 40740231, 2025). "IHC analysis of six paired PC samples revealed significantly higher MRPL3 expression in tumor tissues than in normal tissues." (PMID 40740231, 2025). "Single-cell RNA-seq analysis (GSE154778) revealed that MRPL3 was markedly elevated in tumor cells compared to endothelial and fibroblast cells." (PMID 40740231, 2025). "Next, we analyzed the survival profile of MRPL3 in 33 tumors using Hazard Ratio (HR) values to indicate their prognosis and found that MRPL3 was correlated with a poor prognosis in the majority of tumor types, as was the case for TCGA-HCC." (PMID 39868366, 2024). "Consistent with this concept, we observed significantly higher stemness scores in patients with high MRPL3 expression, suggesting that MRPL3 may indicate a more aggressive tumor phenotype and serve as a prognostic marker for PC." (PMID 40740231, 2025). "In addition, immune cell infiltration and tumor mutational burden (TMB) analyses were conducted to explore the relationship between MRPL3 expression and the tumor microenvironment." (PMID 40740231, 2025). "Finally, we performed MRPL3 knockdown experiments in PC cell lines to elucidate its effects on tumor cell proliferation, migration, and invasion." (PMID 40740231, 2025). "These researches demonstrated that MRPL3 may serve as a target to inhibit HCC tumor progression, thus providing strong support for clinical decision-making." (PMID 39868366, 2024). "Targeting MRPL3 through immunotherapy may help rebalance the M1/M2 ratio by reprogramming M2-like macrophage metabolism, potentially enhancing tumor treatment." (PMID 39868366, 2024). "Thus, increased Th2 infiltration associated with high MRPL3 expression may suppress CD8 + T and NK cell activity, thereby fostering an immunosuppressive environment that promotes tumor progression 27-29." (PMID 40740231, 2025). "MRPL3 was found to be overexpressed in LUAD tissues and correlated with poor prognosis, advanced tumor stage, and an immunosuppressive tumor microenvironment." (PMID 42238598, 2026). "LASSO regression identified MRPL3 expression, CA19-9 levels, total bilirubin levels, tumor location, and histological grade as prognostic indicators of OS." (PMID 40740231, 2025). "Tumor immune dysfunction and exclusion (TIDE) scores and drug sensitivity analyses were used to assess the therapeutic implications of MRPL3." (PMID 40740231, 2025). "Our study revealed a significant correlation between MRPL3 expression and poor prognosis in HCC, highlighting its role in metabolic adaptation and tumor progression." (PMID 39868366, 2024). "To further elucidate the mechanistic relevance of MRPL3 in HCC, we explored its roles in lactylation and mitochondrial functions, which revealed its potential as a crucial mediator in tumor metabolic reprogramming and epigenetic regulation." (PMID 39868366, 2024). "MRPL3 was found to be overexpressed in HCC, playing a critical role in tumor growth and metastasis." (PMID 39868366, 2024). "We venture to speculate in this paper that there may be some as-yet-unknown mechanism of interaction between MRPL3 and HIBCH capable of modulating the progression of tumor and thus interfering with respiration and the TCA cycle." (PMID 39868366, 2024).
mitochondrial disease (1 paper, 2022). "Mitochondrial disease-causing mutations were found in thirteen small ribosomal subunit mitoribosomal proteins (MRPS1, MRPS2, MRPS6, MRPS7, MRPS9, MRPS11, MRPS14, MRPS16; MRPS22, MRPS23, MRPS25, MRPS34, MRPS39) and four large ribosomal mitochondrial proteins (MRPL3, MRPL12, MRPL24, MRPL44)." (PMID 36140315, 2022).
MRPL3 also shares sentences with these, for which no sentence is quoted: lung adenocarcinoma (2 papers); lung cancer (2); cardiac disease (1); cardiomyopathy (1); chronic kidney disease (1); colon cancers (1); kidney disease (1); prostate carcinoma (1); triple-negative breast carcinoma (1); uterine corpus endometrial carcinoma (1).